HELLS (helicase, lymphoid specific)
Diseases named in the same sentence as HELLS in open-access papers (continued):
Sharing a sentence is not in itself a finding about the gene and the disease.
prostate carcinoma (4 papers, 2016 to 2025). A carcinoma that arises from epithelial cells of the prostate gland. "Our data are consistent with several large-scale CRISPR screen-based studies that have also identified HELLS as a key mediator of PARPi sensitivity in various cell lines, including those from triple-negative breast cancer, ovarian cancer, and prostate cancer." (PMID 41297801, 2025). "ZIC5 mRNA was up-regulated 17 fold (p = 8.4E–07), ZIC2 8 fold (p = 1.3E–05) and HELLS 2 fold (p = 0.006) in Gleason grade 3 tumor glands derived from GS 4 + 3 = 7 as compared to GS 3 + 3 = 6 prostate cancer." (PMID 27191985, 2016). "Our findings that HELLS-deficient HAP1 cells exhibit increased sensitivity to PARP inhibition are consistent with several CRISPR screen-based studies identifying HELLS as a mediator of PARPi sensitivity in breast, ovarian, and prostate cancer." (PMID 41297801, 2025). "Of these three genes, HELLS and ZIC5 protein expression was strongly associated with GS ≥ 7 prostate cancer, while we were not able to confirm this relation on protein level for ZIC2." (PMID 27191985, 2016).
osteosarcoma (3 papers, 2018 to 2020). A usually aggressive malignant bone-forming mesenchymal neoplasm, predominantly affecting adolescents and young adults. "To study the role of HELLS overexpression in osteosarcoma, we acquired a lentivirus encoding an shRNA sequence complimentary to HELLS (shHELLS) to facilitate HELLS gene knockdown in osteosarcoma cell lines, as well as vector-only control." (PMID 30220967, 2018). "Further, we evaluated the role of HELLS in osteosarcoma cell survival, proliferation, migration, and tumorigenesis both in vitro and in vivo." (PMID 30220967, 2018). "We confirmed HELLS gene upregulation in the human osteosarcoma cell lines 143B, SJSA-1, and SaOS-2, as well as in four of the five independent patient-derived orthotopic xenografts used in this study." (PMID 30220967, 2018). "We also showed that RB-E2F pathway inactivation, present in most osteosarcomas, results in increased HELLS expression." (PMID 30220967, 2018). "At the protein level, HELLS was also highly overexpressed across all analyzed osteosarcoma subjects compared to MSCs and human osteoblasts (hOB) controls." (PMID 30220967, 2018). "To determine if HELLS is overexpressed in osteosarcoma, we blasted The Cancer Genome Atlas (TCGA) data set and found that HELLS is upregulated in sarcoma tumor samples compared to normal controls." (PMID 30220967, 2018). "HELLS knockdown in osteosarcoma cell lines results in modest reduction (31.6–40.5%) in the ability to form colonies when compared to controls, but reached statistical significance in 143B and U-2 OS cell lines." (PMID 30220967, 2018). "We also found that HELLS mRNA is upregulated and its protein overexpressed in osteosarcoma." (PMID 30220967, 2018). "To confirm direct transcriptional regulation of E2F1 on HELLS in human osteosarcoma, we acquired lentiviral vectors encoding shRNAs targeting E2F1 (shE2F1) and transduced the four human osteosarcoma cell lines in which we had previously observed HELLS overexpression." (PMID 30220967, 2018). "Here, we show that HELLS is overexpressed in osteosarcoma; however, our results indicate that while HELLS is a good biomarker for RB pathway deregulation, HELLS does not contribute to osteosarcoma tumorigenesis." (PMID 30220967, 2018). "Despite the lack of mRNA upregulation in some cell lines and tumors, HELLS protein overexpression was observed in all the human osteosarcoma cell lines and xenografts analyzed in this study." (PMID 30220967, 2018). "Interestingly, we found that E2F1 knockdown was not effective at reducing HELLS protein levels in any of the osteosarcoma cell lines used." (PMID 30220967, 2018). "This suggests that while HELLS may serve as a biomarker for tumorigenesis and for RB-E2F pathway status, it is unlikely to serve as a relevant target for therapeutics in osteosarcoma." (PMID 30220967, 2018). "Therefore, it is not surprising that HELLS upregulation and overexpression in osteosarcoma is not restricted to RB1-null cases, but rather a generalized event observed across samples that bear RB-E2F pathway inactivation." (PMID 30220967, 2018).
triple-negative breast carcinoma (3 papers, 2020 to 2025). An invasive breast carcinoma which is negative for expression of estrogen receptor (ER), progesterone receptor (PR), and human epidermal growth factor receptor 2 (HER2). "In agreement with the PARPi sensitivity that we observed, the HELLS gene was identified in a genome-wide shRNA screen for olaparib sensitivity, and as part of a gene signature associated with response to PARP inhibition in a panel of triple-negative breast cancer cell lines." (PMID 31802118, 2020).
head and neck squamous cell carcinoma (2 papers, 2012 to 2022). A squamous cell carcinoma that arises from any of the following anatomic sites: lip and oral cavity, nasal cavity, paranasal sinuses, pharynx, larynx, and salivary glands. "In head and neck squamous cell carcinoma, the oncogene FOXM1, a downstream target of the oncogenic SHH signaling pathway, upregulates HELLS, and HELLS is then responsible for promoter hypermethylation of tumor suppressors such as CDKN2A." (PMID 36012581, 2022).
medulloblastoma (2 papers, 2019 to 2021). A malignant, invasive embryonal neoplasm arising from the cerebellum. "In SHH stimulated precursor cells and SHH medulloblastoma cell culture, HELLS is upregulated at both the mRNA and protein levels." (PMID 31541170, 2019). "Our finding of YAP1 directed HELLS upregulation in SHH medulloblastoma suggests a role for HELLS regulated chromatin remodeling in SHH medulloblastoma." (PMID 31541170, 2019). "Compared to normal cerebellum, HELLS is expressed at higher levels in all medulloblastomas with the highest expression in the SHH subgroup." (PMID 31541170, 2019). "Densitometry and statistical analysis indicate 3.3 ± 0.4 (mean ± S.E.M., N = 8) higher levels of HELLS protein in NeuroD2:SmoA1 mouse medulloblastoma tumors." (PMID 31541170, 2019). "However, knockdown of YAP1 in murine medulloblastoma slice culture also resulted in decreased levels of HELLS mRNA and protein, indicating that HELLS is regulated through YAP1." (PMID 31541170, 2019). "As other epigenetic regulators have been targeted for cancer treatment with varying degrees of success, future studies to determine HELLS role in SHH medulloblastoma may lead to new avenues of research and eventually to new therapeutic interventions." (PMID 31541170, 2019). "Since we observed increased levels of HELLS in SHH stimulated CGNPs, and in the developing murine cerebella, we next sought to determine whether HELLS is upregulated in human medulloblastoma." (PMID 31541170, 2019). "Our results indicate a possible role for HELLS in the proliferative program of SHH in both development and medulloblastoma." (PMID 31541170, 2019). "Here, we investigated HELLS expression and regulation in murine cerebellar development and SHH medulloblastoma." (PMID 31541170, 2019). "Here we have identified YAP1 mediated, Sonic hedgehog induced upregulation of HELLS in murine models of cerebellar development and SHH medulloblastoma." (PMID 31541170, 2019). "SHH medulloblastoma is characterized by aberrations in the SHH pathway, so our next question was to determine whether HELLS is upregulated in an SHH medulloblastoma mouse model." (PMID 31541170, 2019). "Indeed, the verteporfin induced decrease in CyclinD1 or D2 in CGNPs and MBCs links the YAP1/HELLS axis to a requirement for proliferation in the developing cerebellum and SHH medulloblastoma tumor cells." (PMID 31541170, 2019). "We observe upregulated HELLS expression in both murine and human SHH medulloblastoma." (PMID 31541170, 2019). "With so many possible functions of HELLS that result in alterations in gene expression, knowing it is expressed at higher levels in CGNPs stimulated with SHH-N led us to hypothesize HELLS involvement in cerebellar development and medulloblastoma." (PMID 31541170, 2019).
renal cell carcinoma (2 papers, 2018 to 2019). "Increased HELLS expression was associated with poor prognosis in patients with renal cell carcinoma." (PMID 30042885, 2018).
acute myeloid leukemia (1 paper, 2026). Acute myeloid leukemia (AML) is a group of neoplasms arising from precursor cells committed to the myeloid cell-line differentiation. "Analysis from cancer databases revealed HELLS upregulation in several cancers, including acute myeloid leukemia (AML)." (PMID 42214672, 2026).
epithelial dysplasia (1 paper, 2026). "Immunohistochemistry (IHC) was used to identify stem cell biomarkers in tissue samples, most studies demonstrated that higher expression of stem cell markers (CD44, ALDH1, HELLS, TARIF, SOX2, NANOG, and CD147) correlated with severity of epithelial dysplasia." (PMID 41778103, 2026).
gynecological cancers (1 paper, 2025). "In conclusion, our findings indicate that the expression of 6-CRRGs, including APOBEC3B, HELLS, SLC15A3, CDA, RHOB and UPP1, is associated with the prognosis of patients with common gynecological cancers." (PMID 39944833, 2025).
leiomyosarcoma (1 paper, 2022). An uncommon, aggressive malignant smooth muscle neoplasm, usually occurring in post-menopausal women. "Compared to other histological types, leiomyosarcoma showed high expression of HELLS, EPAS1, NQO1 and low expression of IL6." (PMID 34982796, 2022).
lymphoma (1 paper, 2021). A malignant (clonal) proliferation of B- lymphocytes or T- lymphocytes which involves the lymph nodes, bone marrow and/or extranodal sites. "Since HELLS is expressed in many tumors and plays a relevant role in the transcription and genomic stability of cancers, its pharmacological inhibition may represent a promising therapeutic strategy in lymphomas and in other human neoplasms." (PMID 33504766, 2021).
myeloid leukemia (1 paper, 2025). A clonal proliferation of myeloid cells and their precursors in the bone marrow, peripheral blood, and spleen. "HELLS protein expression is significantly elevated in various malignant cell lines, including those derived from myeloid leukemia." (PMID 41297801, 2025).
myeloma (1 paper, 2021). "Interestingly, this PHF19high myeloma cell subpopulation seems to be the cell cycling fraction as they also exhibited high expression of genes involved in cell cycling including HELLS, EZH2, TYMS, ZWINT, and MKI67." (PMID 34857028, 2021). "Interestingly, this PHF19 high myeloma cell subtype also exhibited high expression of genes involved in cell cycle including HELLS, EZH2, TYMS, ZWINT, and MKI67." (PMID 34857028, 2021).
oral cancer (1 paper, 2009). "In conclusion, the potential of FOXM1B, CEP55 and HELLS as early oral cancer biomarkers deserves further investigation." (PMID 19287496, 2009). "Our finding that FOXM1 is upregulated early during oral cancer progression renders FOXM1 an attractive diagnostic biomarker for early cancer detection and its candidate mechanistic targets, CEP55 and HELLS, as indicators of malignant conversion and progression." (PMID 19287496, 2009).
oropharyngeal squamous cell carcinomas (1 paper, 2018). "Overexpression of HELLS was also reported in prostate and oropharyngeal squamous cell carcinomas;." (PMID 30042885, 2018).
pancreatic ductal adenocarcinoma (1 paper, 2021). An infiltrating adenocarcinoma that arises from the epithelial cells of the pancreas. "HELLS was overexpressed in pancreatic ductal adenocarcinoma compared with that in the normal samples in Grutzmann’s dataset, with a fold change of 2.596 and a P value of 0.005." (PMID 34315468, 2021).
steatosis (1 paper, 2019). Increased lipid within the cytoplasm of cells. "The analysis of genes identified in NAFL-Steatosis patients and NAFL-NASH patients (n = 58 genes) and in NASH patients (n = 141 genes) with high MMP9 level showed that 4 genes, FABP4, MMP9, HELLS and TREM2, were shared between these three groups of patients." (PMID 31874999, 2019).
vitiligo (1 paper, 2021). Generalized well circumscribed patches of leukoderma that are generally distributed over symmetric body locations and is due to autoimmune destruction of melanocytes. "The hub genes of vitiligo melanocytes include CDK1, HSP90AA1, AKT1, BCL2L1, HDAC2, HELLS, and KIF23." (PMID 33790887, 2021).
tumor (44 papers, 2012 to 2025). "The HELLS gene encodes a chromatin remodeler, which is expressed in tumor tissues and its overexpression is associated with poor prognosis." (PMID 34117218, 2021). "Pioneer studies have shown that HELLS acts as a tumor suppressor and influences cellular metabolism, such as lactate production or the regulation of tricarboxylic acid (TCA) cycle intermediates through its control of fumarate hydratase expression." (PMID 40175344, 2025). "The results revealed that when the prognostic indicator was OS, high grade residual tumor, metastasis, positive margin status, high expression of HELLS and STMN1, low expression of EPAS1, CXCL2, NQO1, IL6 were associated with poor prognosis." (PMID 34982796, 2022). "In RB, HELLS was initially identified along with UHRF1 as candidate genes contributing to tumor progression in murine RB models." (PMID 32840881, 2021). "The chromatin remodeler HELLS was found to regulate various tumor suppressors through an epigenetic pathway in several cancers." (PMID 33280236, 2021). "We found that HELLS is upregulated in PC tissues and correlates with advanced clinical stage and a poor prognosis, and the knockdown of HELLS leads to tumor growth arrest and increased sensitivity to cisplatin." (PMID 33280236, 2021). "In summary, our work firmly demonstrated an oncogenic role of HELLS, which promotes tumor growth and decreases the sensitivity to cisplatin in PC." (PMID 33280236, 2021). "Since Rb1/p107/Hells TKO mice develop tumors at a reduced frequency and with slower progression rates than Rb1/p107 DKO mice, we aimed to identify pathways regulated by HELLS that aid in the delayed tumor progression." (PMID 32071286, 2020). "That HELLS expression in MBCs was abrogated to a greater extent than in CGNPs with lower doses of verteporfin seems to confirm the tumor-specific importance of HELLS." (PMID 31541170, 2019). "Further, we pioneered the study of Hells in developmental tumor models by generating Hells conditional knockout osteosarcoma mouse models to examine the role of HELLS in osteosarcoma tumor development." (PMID 30220967, 2018). "Others and we have identified HELLS as a transcriptional downstream target gene of aE2Fs that is overexpressed in cancer and contributes to tumor progression." (PMID 30220967, 2018). "HELLS was expressed in > 1% of tumor cells in 8/30 (27%) GS 4 + 3 = 7 cases as compared to 20/142 (14%) of GS 3 + 4 = 7 tumors (p = 0.09)." (PMID 27191985, 2016). "Considering the substantial overexpression of HELLS in various tumor types, it is possible that HELLS in addition to promoting cancer cell proliferation, may also aid tolerance of elevated ROS-induced DNA damage and replication stress." (PMID 41297801, 2025). "Additionally, G6PD, HELLS, RRM2, and STMN1 were positively associated with higher tumor stage, grade, age, sex, and ethnicity, suggesting an influential contribution to the pathogenesis of HCC." (PMID 36304446, 2022). "We speculated that the overexpression of HELLS promotes PC growth by repressing several tumor suppressors." (PMID 33280236, 2021). "Many downregulated genes in tumour‐infiltrating peripheral CD8+ T cells are associated with classical IFN responses (IFI6, IFI27, MX1, STAT1, EPSTI1 PARP9, ISG15), cell proliferation (STMN1, CENPF, HELLS, NUSAP1, and DNPH1), and T cell costimulation (CD28, TMIGD2, TNFRSF4, CD27, and TNFRSF18)." (PMID 39350478, 2024).